CD4 (CD4 molecule)
Diseases named in the same sentence as CD4 in open-access papers (continued):
Sharing a sentence is not in itself a finding about the gene and the disease.
HIV-1 infection (continued). "Naturally occuring Treg (nTreg) (CD4+CD25+Foxp3+) exist in all individuals and play a critical role in chronic HIV-1 infection." (PMID 20455275, 2010). "Because a systemic inflammatory disorder and immune hyperactivation represent also key features of the HIV-1 infection, we first assessed DCIR expression in CD4+ T cells isolated from infected individuals." (PMID 21085612, 2010). "Although NBD-556 inhibits HIV-1 infection of CD4+CCR5+ cells, it can replace CD4 and thus enhance HIV-1 infection of CD4−CCR5+ cells." (PMID 19343205, 2009). "Infectivity was tested using HeLa-CD4-LTR-β-gal reporter (MAGI) cells, which contain a stably-integrated LTR-β-galactosidase expression cassette that reports productive HIV-1 infection following Tat expression and transactivation." (PMID 19901984, 2009). "Persistent exposure to antigen, such as occurs in HIV-1 infection, is believed to generate short-lived IFN-γ producing effector memory CD4+ T cells which are impaired in their ability to develop into IL-2 producing central memory cells." (PMID 19352428, 2009). "Apart from the decline in CD4+ T cell numbers, HIV-1 infection also impairs the functional and phenotypic heterogeneity of HIV-1 specific CD4+ T cells." (PMID 19352428, 2009). "Prior to studying the resistance of an R88-A3G expressing cell line to HIV-1 infection, we characterized the possible impact of stable expression of R88-A3G on cell growth and expression of an HIV receptor, CD4." (PMID 18414671, 2008). "Human cell lines that express CD4 and CXCR4 generally should support productive T cell-tropic HIV-1 infection." (PMID 18665212, 2008). "This forms the basis of understanding HIV-1 immunopathogenesis, as well as providing the rationale for the design of immunotherapeutic strategies aimed at inducing virus-specific CD4+ and CD8+ T-cell responses, in chronic HIV-1 infection." (PMID 18976455, 2008). "Moreover, we established CD4+ C8166 T cell lines that stably express either R88-A3G or HA-A3G by transduction with VSV-G-pseudotyped lentiviral vector that harbor expression cassettes for R88-A3G or HA-A3G, respectively, and tested their susceptibility to Vif+ HIV-1 infection." (PMID 18414671, 2008). "In line with results previously reported with HIV-1 infection in vitro, endogenously HIV-1 infected CD4+ T cell blasts selectively down-modulated HLA-A and –B alleles while the expression of HLA-C and HLA-E molecules was conserved." (PMID 18617991, 2008). "It has also been reported that HIV-1 infection in vitro results in a selective down-modulation of MHC-I molecules in cell lines and in exogenously infected primary CD4+ T cells." (PMID 18617991, 2008). "We assessed the relationship of HSV-1/HSV-2 co-infection status on CD4+ T cell counts and HIV-1 RNA levels over time prior in a cohort of 186 treatment naïve adults identified during early HIV-1 infection." (PMID 17957262, 2007). "During acute and early HIV-1 infection (AEI), there is selective depletion of CD4+ T cells in the gastrointestinal (GI) lamina propria (LP) compared with levels measured in the peripheral blood." (PMID 17147468, 2006). "Further prospective studies may help determine whether associations between low serum selenium and low CD4 count and more advanced HIV-1 disease could be related to the frequent occurrence of hypoalbuminemia and the acute phase response in people with advanced HIV-1 infection." (PMID 16712720, 2006). "During acute and early HIV-1 infection (AEI), up to 60% of CD4+ T cells in the lamina propria of the lower gastrointestinal (GI) tract are lost as early as 2–4 wk after infection." (PMID 17147468, 2006). "During HIV-1 infection immune hyperactivation is accompanied by up-regulation of surface expression of CD38 and HLA-DR on CD4 and CD8 T cells." (PMID 16181494, 2005).
HIV-1 infection (continued). "The presence of non-neutralizing antibodies in plasma during early-stage HIV-1 infection would support the use of CD4-mimetic compounds as an early intervention to decrease the size of the latent HIV-1 reservoir by eliminating infected cells." (PMID 40689664, 2025). "In the vast majority of people living with HIV (PLWH), HIV-1 infection elicits non-neutralizing antibodies directed against CD4-induced (CD4i) epitopes." (PMID 40689664, 2025). "Quantification of these effects demonstrates a significant reduction in wild-type HIV-1 infection in cells expressing CD4-targeting shRNA, not observed when these cells were infected with VSV-G pseudotyped HIV-1 virus." (PMID 40029073, 2025). "Our previous results showed that the expression levels of m6A writers and erasers were not altered by HIV-1 infection in primary CD4+ T cells or latently infected cells after reactivation." (PMID 41085277, 2025). "Macrophages and CD4+ T cells are the primary target cells of HIV-1 infection, depending on HIV-1 subtypes, while monocytes are not primary target cells for HIV-1 as they are resistant to productive HIV-1 infection (67, –, 69)." (PMID 40434097, 2025). "The edited human CD4+ T cells showed resistance to X4-tropic HIV-1 infection, as evidenced by reduced p24 levels, with no detectable off-target effects or toxicity." (PMID 40003685, 2025). "Knocking down FNBP1L, ARHGAP24, and ATP6V1B1 in CD4+ T cells did not enhance HIV-1 infection, contrasting sharply with the significant effects observed in MDDCs." (PMID 40029073, 2025). "Instead, these findings support a scenario where non-infected activated CD4+ T cells boost macrophage HIV-1 infection through a multilayered cellular mechanism, potentially involving the CD4:TCR to MHCII axis." (PMID 40130873, 2025). "Although treatment with LC also impaired the ability of HIV-1 to down-regulate CD96 from the cell surface, it is difficult to clearly conclude on this, since LC interfered with productive HIV-1 infection, was slightly cytotoxic, and reduced CD96 cell surface levels also in uninfected CD4+ T cells." (PMID 40911682, 2025). "Though we did not test the effect of DNM2 knockdown on HIV-1 infection in CD4+ T cells, the increase in infection observed upon DNM2 knockdown in MDDCs in our study suggests cell-specific differences in the reliance on dynamin-2-mediated endocytosis." (PMID 40029073, 2025). "Sterile alpha motif (SAM) and histidine-aspartate (HD) domain-containing protein 1 (SAMHD1) restricts HIV-1 infection in non-dividing immune cells, such as resting CD4+ T cells, macrophages, and dendritic cells." (PMID 40434097, 2025). "Clearly, pre-stimulation of autologous non-infected CD4+ T cells with PHA was found to be essential to boost HIV-1 infection of macrophages." (PMID 40130873, 2025). "We have reported that HIV-1 infection upregulates m6A levels of total cellular RNA in CD4+ T cells without changing the expression of m6A writers and erasers." (PMID 41085277, 2025). "Both CD4+ and CD8+ T-cells expressing CD103/ItgαE and CD69 are affected during HIV-1 infection." (PMID 41227377, 2025). "Interestingly, HIV-1 infection increased PLIN3 mRNA levels and nuclear localization but reduced PLIN3 protein expression in primary CD4+ T cells." (PMID 41085277, 2025). "This suggests that the enhancing effect of CD4+ T cell coculture on HIV-1 infection in macrophages is not primarily attributed to virus amplification in the CD4+ T cell fraction." (PMID 40130873, 2025). "Overall, our results demonstrate that HIV-1 infection does not alter the RNA or protein levels of PLIN3, and PLIN3 KO does not change HIV-1 infection in Jurkat CD4+ T cells." (PMID 41085277, 2025). "In HIV-1 infection, CCR5 serves as a major co-receptor facilitating viral entry into CD4+ T cells." (PMID 41009690, 2025). "The majority of CD4 T cells die not from productive HIV-1 infection but from abortive infection, where the virus initiates replication but fails to complete it." (PMID 40072080, 2025).
HIV-1 infection (continued). "Our results show that the depletion of FNBP1L, ARHGAP24, and ATP6V1B1 enhances HIV-1 infection in MDDCs, but not in CD4+ T cells." (PMID 40029073, 2025). "Conversely, elevated levels of activated CD4+ T cells, which indicate a negative prognosis, were observed during the acute phase of HIV-1 infection." (PMID 38999941, 2024). "Future studies using blood or tissue CD4+ T cells collected from HIV-1 patients with viremia and on suppressive antiretroviral therapy will be useful in determining how m6A levels are affected by HIV-1 infection in vivo." (PMID 38257827, 2024). "For example, upregulation of miR-4516 in response to productive HIV-1 infection has been independently reported in both PBMC and CD4+ T cells; the observation reported in PBMC may be due only to CD4+ T cells, which constitute a major fraction of PBMC." (PMID 38790203, 2024). "Finally, infectivity and modulation of CD4 expression on Vδ1 T cells from HIV-seronegative donors revealed de novo expression of CD4 following TCR stimulation, indicating a potential window of opportunity of increased permissibility to HIV-1 infection." (PMID 39149467, 2024). "Importantly, a significant T cell depletion after HIV-1 infection occurs in the GALT, which recovers slowly, even after restoring the CD4+ T cell levels due to strict adherence to cART." (PMID 38400005, 2024). "Additionally, HIV-1 infection of PBMC and CD4+ T cells induces the expression of the circular RNA (circRNA) ciTRAN, which promotes viral transcription by interacting with the HIV-1 restriction factor SRSF1." (PMID 38790203, 2024). "In addition to the finding that CD4+ type I NKT cells are also permissive to HIV-1 infection, it has also been shown that HIV-1 infection can interfere with CD1d expression and thus, CD1d-dependent activation of type I NKT cells." (PMID 39355244, 2024). "Unexpectedly, we uncovered a tissue-specific effect of menopausal status on HIV-1 infection susceptibility, with changes in HIV-1 infection target cell density and CD4+ T cell infection frequency only observed in the EM and not the CX nor ECX." (PMID 39872519, 2024). "To infer mechanisms by which HIV-1 infection induces the differential expression of EREs in the gut, we next quantified changes in expression resulting from IFN-I stimulation of uninfected gut-derived CD4+ T cells." (PMID 38677181, 2024). "The known functions of CPSF6 in nuclear import and integration site selection are not sufficient to explain the enhanced permissivity to HIV-1 infection observed upon CPSF6 knock-out in primary CD4 + T cells." (PMID 39678349, 2024). "The study demonstrated that viral suppression, CD4 gains, adverse events, quality of life, and patient satisfaction were comparable between groups, confirming DTG + FTC’s safety and efficacy for long-term management of HIV-1 infection." (PMID 39507885, 2024). "In response to HIV-1 infection or stimulation by interferon, viperin is an ISG highly induced in macrophages, relative to the low levels of induction observed in monocyte-derived DCs and CD4+ T cells." (PMID 39205255, 2024). "HIV-1 infection did not affect the cytokine profile of the T helper CD4+ cells, since flow cytometry analysis two days after virus infection confirmed that the cells preserved their polarized cytokine expression profile (data not shown)." (PMID 37415979, 2023). "Further work is needed to validate TE-KZNF regulatory interactions in T cells, probe their connection to epigenetic variation at individual TE loci, and explore their repercussions on gene expression variation in CD4+ T cells, with and without HIV-1 infection." (PMID 38168352, 2023). "We did not detect opioid receptor mRNA in human PBMCs, CD4+ T cells or monocyte-derived macrophages, and opioids had minimal effect on HIV-1 infection and replication in vitro." (PMID 36851631, 2023).
HIV-1 infection (continued). "In that study, CD4 counts and viral loads of the HIV-1-infected subjects were not significantly different from the subjects of this Ad26.COV2.S vaccinated cohort, arguing against HIV-1 infection being a major factor for the observed poor vaccine response." (PMID 37067754, 2023). "APCs from HIV-1-positive non-progressors (NPs) who control their HIV-1 infection in the absence of ART do not trans-infect CD4+ T cells." (PMID 38140588, 2023). "As previously shown, HIV-1 infection of primary CD4+ T cells failed to induce or very weakly induced (in cells from donor I) type I IFN production and the IFN-responsive genes ISG15, IFIT1, and IFIT2." (PMID 37922361, 2023). "Our study suggests that IL-15 plays confounding roles in HIV-1 infection, and future studies on the IL-15–based boosting of anti–HIV-1 immunity should carefully examine the potential effects on the expansion of HIV-1 reservoirs in CCR5+CD4+ T cells." (PMID 36821374, 2023). "In contrast to our results from clinical samples, we did not see any effects of direct morphine exposure on HIV-1 infection or latency reactivation in primary CD4+ T cells in vitro." (PMID 36851631, 2023). "In the primary CD4+ T cells, phospho-p105 was detected in all conditions, including uninfected cells, due to NF-κB activation induced by the CD3/CD28 co-stimulation conducted prior to HIV-1 infection." (PMID 37341489, 2023). "With untreated HIV-1 infection, the numbers of CD14+ cells in HIV-1-infected BLT mice were relatively stable, while the number of CD4+ cells declined with duration of replication consistent with replication-induced death of CD4+ cells." (PMID 37406092, 2023). "Althought CD4+ T cells percentages and CD4/CD8 T cell ratio were equivalent in both groups before HIV-1 infection and VX-765 treatment, percentages of circulating CD4+ T cells and CD4/CD8 T cell ratio at day 22 post-infection in the VX-765-treated group were slightly higher (p<0.05)." (PMID 36800238, 2023). "IL-15, but not IL-7, improved the survival of CCR5+CD4+ T cells, drove their expansion, and facilitated HIV-1 infection in vitro and in humanized mice." (PMID 36821374, 2023). "Over 95% of CD4 T cells are non-permissive to HIV-1 infection and accumulates incomplete DNA transcripts in their cytosol." (PMID 36800238, 2023). "Although most Ukrainian PLWH arriving in Sweden had undetectable plasma viraemia, a substantial proportion of them were viraemic, had low CD4+ T-cell counts or were not aware of their HIV-1 infection." (PMID 38037731, 2023). "Previous reports indicated that IFI16 restricts HIV-1 infection trough STING in macrophages but promotes HIV-1 induced CD4+ T cells death by pyroptosis and thus may drive HIV-1 pathogenesis." (PMID 36800238, 2023). "Additionally, IRPs are central to the homeostatic proliferation and differentiation of CD4 and CD8 T cells in HIV-1 infection." (PMID 36408648, 2023). "These epithelial cells are not natural targets for HIV-1 infection; however, we confirmed resistance to dCA in primary CD4+ T cells." (PMID 37112931, 2023). "We previously demonstrated that fusion protein CLDs consisting of the D1D2 domain of CD4 and the neck domain (ND) and carbohydrate-recognition domain (CRD) of DC-SIGN produced in E. coli could efficiently inhibit HIV-1 infection in vitro and ex vivo." (PMID 35891347, 2022). "These patients are characterized by years of HIV-1 infection, long-term asymptomatic status, and normal CD4+T cell count without ART, classified as HIV-infected long-term nonprogressors (LTNPs) and elite controllers (ECs)." (PMID 35211115, 2022). "To further elucidate the antiviral potential of reprogrammed CD8+ T cells, we evaluated the capacity of nonstimulated cells from noncontroller individuals under ART to suppress HIV-1 infection of autologous CD4+ T cells." (PMID 35380989, 2022).
HIV-1 infection (continued). "In human CD4+ T cells, GPI-10E8 and its bifunctional derivatives blocked both CCR5- and CXCR4-tropic HIV-1 isolates efficiently, and the modified cells displayed robust survival selection under HIV-1 infection." (PMID 34821542, 2022). "To simulate HIV-1 infection in cell culture, we transfected HEK293 cells or electroporated Jurkat cells, an immortalized line of human CD4+ T-cell lymphocytes, with a lentiviral vector (pfNL43-dE-EGFP) encoding the HIV-1 genome whose expression is driven by long terminal repeats." (PMID 35181598, 2022). "Since MSCs express CD4, CXCR4 and CCR5 receptors/co-receptors that are required for HIV-1 infection, studies in vitro have sought to establish whether MSCs could be infected with the virus." (PMID 34973144, 2022). "Moreover, the TKO hu-PBMC model supports HIV-1 infection via the intraperitoneal, rectal, or vaginal route, as confirmed by robust plasma HIV viremia and CD4+ T cell depletion." (PMID 34818071, 2022). "LP GZB+ CD4 T cells were present at low frequencies in the absence of HIV-1 infection (controls: median 1.8% of CD4 T cells, range: 0.37–3.0)." (PMID 35258402, 2022). "Antiretroviral therapy controls, but does not cure, HIV-1 infection due to a reservoir of rare CD4+ T cells harboring latent proviruses." (PMID 36070690, 2022). "It enters all cells with equal efficiency, independent of CD4 expression levels, and integrates its genome to express luciferase as an indicator of HIV-1 infection and integration." (PMID 35216446, 2022). "However, in addition to macrophages, Vpr enhances HIV-1 infection and HIV-1 gene expression in CD4+ T cells." (PMID 35746791, 2022). "The effect of SPHK inhibition on limiting HIV-1 infection in CD4 T cells was observed irrespective of the biological sex or age of the donor, with neither the variable of biological sex nor that of age reducing the effectiveness of SPHK inhibition." (PMID 35412343, 2022). "Despite effective control of HIV-1 replication with antiretroviral therapy (ART), a significant proportion of treated persons fails to increase CD4+ T cell counts to levels observed in individuals without HIV-1 infection." (PMID 35316209, 2022). "Besides resting memory CD4+ T cells, cells of the myeloid lineage, especially macrophages, are believed to be an important sanctuary for HIV-1, due to their ability to spread HIV-1 infection in immune-privileged sites." (PMID 36131914, 2022). "We did not screen HIV-1 infection, but none of the participants was receiving treatment with immunosuppressors or presenting an abnormal CD4+ T cell count, which generally becomes impaired in the presence of HIV infection." (PMID 35741850, 2022). "In addition to CD4+ T lymphocytes (CD4TL), cells of the macrophage (MΦ)-monocyte lineage are HIV-1 target cells that play a central role in the pathophysiology of HIV-1 infection leading to AIDS." (PMID 35622876, 2022). "The effect of SPHK inhibition on limiting HIV-1 infection in CD4 T cells was observed irrespective of the biological sex or age of the donor, with neither variable significantly influencing the effectiveness of SPHK inhibition." (PMID 35412343, 2022). "No antiviral activity of CL1.1 against either HIV-1 infection of human primary CD4+ T cells or SARS-CoV-2 infection of Vero E6 cells was detected using flow cytometry." (PMID 36040168, 2022). "For example, CD4+ TSCM cells may support viral replication and transcriptionally silenced forms of infection in HIV-1 infections." (PMID 36059484, 2022). "HIV-1 infection requires lifelong treatment with antiretroviral therapy (ART) due to viral rebound of a latent reservoir of intact, transcriptionally silent provirus found to persist in the genome of CD4+ T cells." (PMID 35042816, 2022). "We next investigated the relevance of three host factors that have been shown to affect HIV-1 infection in other cell systems, but whose role during infection of resting CD4+ T cells has not been defined." (PMID 34949807, 2022).